CGAS (cyclic GMP-AMP synthase)
Diseases named in the same sentence as CGAS in open-access papers (continued):
Sharing a sentence is not in itself a finding about the gene and the disease.
COVID-19 (continued). "mtDNA that accumulates in the blood activates the cGAS-STING pathway, triggering inflammatory cytokine and chemokine expression that contribute to the cytokine storm and tissue damage seen in cases of severe COVID-19." (PMID 39375263, 2024). "cGAS/STING activation has been characterized during SARS-CoV-2 infection and may play a central role in the pathogenesis of COVID-19." (PMID 37077526, 2023). "cGAS-STING signaling has been observed to be activated in endothelial cells of human patient skin and lung tissues following infection with SARS-CoV-2, the RNA virus responsible for the global COVID-19 pandemic." (PMID 37941028, 2023). "Our results showed that cGAS expression was neither detected in villous nor fetal membrane tissue sections in placentas with or without exposure to COVID-19 in pregnancy (data not shown)." (PMID 36743911, 2022). "The recognition of delayed STING over-activation in severe COVID-19 patients could prompt to target STING with specific small molecules inhibitors already designed and/or aspirin, which inhibits cGAS." (PMID 33335532, 2020). "Indeed, patients who experienced long-term post-COVID-19 symptoms had higher levels of cGAS, STING and IFN-α than individuals who did not experience LC symptoms." (PMID 41011507, 2025). "However, most old patients with severe COVID-19 never exhibited previous features of SAVI syndromes, so that other explanations than mutations of cGAS-STING must be discussed, which might also be more specific for SARS-CoV infections." (PMID 33335532, 2020). "In the present study, higher levels of STING and cGAS gene expression and plasma levels of IFN-α, IL-6, and TNF-α were identified in patients with the severe form of acute COVID-19 than in patients with the nonsevere form." (PMID 38424312, 2024). "Consistent with the activation of cGAS–STING signalling, phosphorylated STING (p-STING)—a selective marker of activated STING23—was observed in perivascular macrophages in COVID-19 lesions, but not in healthy controls." (PMID 35045565, 2022). "This is supported by elevated gene expressions of cGAS and STING in peripheral blood leukocytes and higher plasma IFN-α in severe (n = 44) and long COVID (n = 30) compared to non-severe (n = 43) and convalescent (n = 31) COVID-19." (PMID 41305428, 2025). "Third, we observed that the SARS-CoV-2 M protein specifically inhibits RIG-I/MDA-5–MAVS signaling rather than TLR3–TRIF or cGAS–STING signaling, a finding that may suggest more precise therapeutic targets for COVID-19." (PMID 33372174, 2020).
Sepsis (44 papers, 2019 to 2026). Sepsis is defined as life-threatening organ dysfunction caused by a dysregulated host response to infection. "Activation of cGAS, a cytosolic receptor recognizing double-stranded DNA, in macrophages is important in sepsis (a life-threatening condition caused by infection)." (PMID 40507879, 2025). "Specifically, the administration of ALDH-2, HET0016, RU.521 or H-151, protects sepsis-associated multiple organ damage via the inhibition of cGAS-STING signaling pathway." (PMID 40379629, 2025). "In our research, we aimed to explore the effect of GUP in the treatment of inflammation, particularly in the cGAS-STING pathway-mediated CLP sepsis, and to investigate the underlying mechanisms of its therapeutic role." (PMID 38904004, 2024). "cGAS-STING signalling is activated during sepsis-induced liver injury and cGAS deficiency in mice significantly attenuates liver injury, liver dysfunction by inhibiting IFN-I responses and hepatocyte death." (PMID 39183465, 2024). "Li’s laboratory further demonstrated increased cGAS-STING pathway in human sepsis and discovered that blocking cGAS-STING pathway prevented sepsis-associated acute liver injury." (PMID 38904004, 2024). "This novel mechanism was found to underlie the inflammatory changes in blood pressure mediated by cGAS, which caused hypotension and tissue hypoperfusion during sepsis." (PMID 37548012, 2023). "Subsequently, severe sepsis inflammation, partly due to cGAS activation, causes further cell death, which more prominently elevates free mtDNA." (PMID 34768881, 2021). "The less severe sepsis in cGAS-/- mice compared with WT mice supported previous reports of less severe CLP in mice with cGAS downstream signaling deficiency (STING and IRF-3)." (PMID 34768881, 2021). "Mitochondria are important for ATP production and mitochondrial free DNA in serum is associated with sepsis severity, partly on account of cGAS activation." (PMID 34768881, 2021). "The responses against sepsis induced by subcutaneous implantation of the Pseudomonas-contaminated catheters in cGAS-deficient (cGAS−/−) mice were lower than in wild-type (WT) mice as indicated by liver enzymes, white blood cell count, cytokines, and M1-polarized macrophages in the spleens." (PMID 40507879, 2025). "Finally, cGAS, as a canonical cytosolic DNA sensor, detects pathogen-derived double-stranded DNA (dsDNA) and endogenous damage-associated molecular patterns released during sepsis-induced cellular stress." (PMID 40995563, 2025). "This study was designed to investigate the cardioprotective role of mangiferin against sepsis-induced heart injury with a focus on mitochondrial DNA (mtDNA) release and cGAS-STING pathway-related inflammation." (PMID 41572319, 2026). "Damaged mitochondria release mtDAMPs, including mtDNA, and the cGAS-STING signaling pathway is known to play a crucial role in mtDNA-induced inflammation in sepsis-induced AKI." (PMID 41227360, 2025). "In conclusion, cGAS−/− mice with catheter-induced infection demonstrated similar burdens of infection (bacteremia and endotoxemia) but, surprisingly, less severe sepsis than WT (serum cytokines and liver enzymes)." (PMID 40507879, 2025). "Although it is still unclear if METosis improves or worsens the conditions of sepsis, the different levels of METosis between WT and cGAS−/− macrophages after LPS induction imply the involvement of the cGAS pathway in METs." (PMID 40507879, 2025). "Inhibiting cGAS-STING protects mice from sepsis, suggesting that overactivation of this pathway accelerates sepsis progression." (PMID 40102400, 2025). "Gelsevirine and Glycyrrhiza uralensis improve sepsis by inhibiting the cGAS‒STING signalling pathway in microglia and macrophages." (PMID 40211890, 2025).
Sepsis (continued). "Less prominent severity of sepsis in cGAS−/− mice than in the WT was demonstrated in catheter-induced sepsis and LPS injection models, partly through the less severe macrophage responses, as supported by RNA sequencing analysis and other parameters." (PMID 40507879, 2025). "In catheter-induced sepsis, cGAS−/− mice demonstrated lower serum cytokines and liver injury than WT with a similar burden of infection (bacteremia, endotoxemia, neutrophilia, and cell-free DNA)." (PMID 40507879, 2025). "This investigation partially elucidates the potential mechanism by which ZBP1-PANoptosome modulates the activation of the cGAS-STING pathway in the setting of sepsis." (PMID 40995563, 2025). "Several studies have indicated that the cGAS-STING pathway operates through a quaternary signaling cascade in sepsis, including pathogen recognition, inflammatory response, initiation of cellular demise, and immune response." (PMID 40995563, 2025). "Severe macrophage activation (such as in sepsis) damages mitochondria partly through oxidative stress, resulting in the releasing of free mitochondrial DNA into the cytosol that activates cGAS." (PMID 41300373, 2025). "The anti-inflammation of cGAS−/− macrophages compared with WT implies the possible use of cGAS inhibitors in sepsis." (PMID 40507879, 2025). "There are studies demonstrating that the cGAS-STING pathway is involved in not only cisplatin-induced, but also sepsis-associated and IR-induced kidney injury." (PMID 41227360, 2025). "Several studies have established the involvement of the cGAS-STING-NLRP3 axis in NLRP3 inflammasome activation during sepsis, with implications in cardiac, pulmonary, and renal injury associated with the condition." (PMID 41327452, 2025). "Mechanistically, sepsis-induced ribosome collision activated the cGAS-STING signaling axis, which in turn recruited NUFIP1 to STING protein complexes." (PMID 40995563, 2025). "In cecal ligation and puncture (CLP)-induced sepsis, cGAS recognized mtDNA in stressed lung epithelial cells, thereby promoting lung inflammation via the STING pathway." (PMID 40507879, 2025). "The search for an inhibitor targeting the regulation of the cGAS-STING pathway is a promising line of research for the treatment of sepsis." (PMID 38904004, 2024). "The cGAS/STING pathway has been shown to associate with both acute and chronic inflammation, as demonstrated in sepsis-induced acute lung injury and fibrosis in several organs." (PMID 37189826, 2023). "The biological importance of this process was further highlighted in a model of sepsis, where cGAS activity was required for the development of hypotension." (PMID 37548012, 2023). "In sepsis, it is likely that the activated cGAS-STING pathway results in pro-inflammatory gene expression, but is unable to trigger the much-needed anti-inflammatory pathways to restore tissue homeostasis." (PMID 37759732, 2023). "Activation of the cGAS-STING pathway seen in sepsis and radiation suppresses the expression of desaturases, resulting in decreased formation of GLA/DGLA/AA/EPA/DHA." (PMID 37759732, 2023). "The activation of PKGI by cGAMP enables the coupling of blood pressure to cytosolic DNA sensing by cGAS, which plays a key role during sepsis by mediating hypotension and tissue hypoperfusion." (PMID 37548012, 2023). "Together these results show that activation of cGAS mediates the reduction of blood pressure and that this process contributes to hypotension and tissue hypoperfusion during sepsis." (PMID 37548012, 2023). "More importantly, cytoplasmic K+ enhanced the binding of dsDNA to the DNA sensor cyclic GMP-AMP synthase (cGAS) and induced the production of type I interferon (IFN-β) by STING pathway, ultimately causing tissue injury in sepsis." (PMID 38022612, 2023). "In a cecal ligation and puncture (CLP)-induced sepsis mouse model, cGAS recognized mtDNA in stressed lung epithelial cells and facilitated lung inflammation via the STING pathway." (PMID 37189826, 2023).
Sepsis (continued). "Through single-cell RNA sequence, genetic approaches, and mass spectrometry, we demonstrate that STING promotes sepsis-induced multiple organ injury by inducing macrophage ferroptosis in a cGAS- and interferon-independent manner." (PMID 35902564, 2022). "The importance of cGAS-STING signaling has been proven that the cGAS inhibitor RU.521 accelerated the recovery of sepsis-induced cardiac dysfunction via intraperitoneal LPS." (PMID 35186921, 2022). "Here, experiments on cGAS deficient (cGAS-/-) mice were conducted using cecal ligation and puncture (CLP) and lipopolysaccharide (LPS) injection sepsis models and macrophages." (PMID 34768881, 2021). "Regarding bacterial control, cGAS has a limited role in sepsis because of the cGAS-dependent anti-bactericidal effect against only intracellular bacteria." (PMID 34768881, 2021). "Although few studies focused specifically on the kidney injury in sepsis, a role for the cGAS–STING pathway in sepsis has been identified." (PMID 34248963, 2021). "Accordingly, cGAS-/- mice exhibited less severe sepsis than the wildtype (WT) mice, as indicated by survival analysis, endotoxemia at 24 h (but not at 6 h post CLP) and serum cell-free DNA (cfDNA) at 6 h (but not at 24 h post CLP)." (PMID 34768881, 2021). "Nevertheless, our data support sepsis hyperinflammation through cGAS activation by either host or microbial DNA." (PMID 34768881, 2021). "Mouse models of sepsis, including cecal ligation and puncture (CLP) and LPS injection, were used to test an impact of cGAS on sepsis severity." (PMID 34768881, 2021). "It is important to note that mtDNA cannot only be sensed by NLRP3, but also by multi-signaling pathways, such as TLR9 and cyclic GMP-AMP synthase, to induce the progression of sepsis." (PMID 33324236, 2020). "Because mitochondrial injury induces the release of mitochondrial DNA (as DAMPs), which activates cGAS, we hypothesized that sepsis would be less severe in cGAS−/− mice compared to wild-type (WT) mice." (PMID 40507879, 2025). "Therefore, supportive data on the role of cGAS in sepsis using different models are essential for translating this topic to the clinical setting." (PMID 40507879, 2025). "In sepsis models, cfDNA promotes macrophage activation through the cGAS-STING pathway, resulting in the production of pro-inflammatory cytokines and recruitment of additional immune cells, which together contribute to inflammatory cell infiltration and apoptosis within lung tissue." (PMID 41327452, 2025). "Drugs that suppress cGAS-STING signaling pathway may also prevent the immunosuppressive state during sepsis, as activation of this pathway induces a senescent phenotype of macrophage, and the released SASP-related cytokines further promote T cell senescence." (PMID 40379629, 2025). "Studies have demonstrated that the cGAS-STING axis is activated by mtDNA in cisplatin-induced and sepsis-associated kidney injury, and suggested that inhibiting the cGAS-STING axis may reduce the damage caused by AKI." (PMID 41227360, 2025). "By identifying PLC-γ and the cGAS-STING pathway as key mediators of these processes, and highlighting the potential of HPX administration, this research offers promising therapeutic strategies for addressing sepsis-associated immune dysfunction." (PMID 40221420, 2025). "Targeted modulation of the cGAS-STING pathway may be an important strategy for the treatment of sepsis." (PMID 38904004, 2024). "If possible, inflammatory contexts leading to the release of the cellular content, such as infected cells that rupture and circulating free DNA during sepsis, could lead to cGAS-STING activation in platelets and contribute to hypercoagulopathy." (PMID 37993259, 2024). "Alleviate sepsis-related ALI by inhibiting mtDNA/cGAS/STING signaling pathway." (PMID 37533869, 2023). "Strategies targeting the cGAS-STING pathway in sepsis and intestinal I/R injury." (PMID 37781354, 2023).
Sepsis (continued). "Therefore, activation of PKGI by cGAMP is an important pathophysiological process because it enables the coupling of blood pressure to cytosolic DNA sensing by cGAS and plays a key role in sepsis, where it mediates hypotension and tissue hypoperfusion." (PMID 37548012, 2023). "Therefore, it is suggested that the abundant PAMPs and DAMPs in the septic microenvironment are associated with the activation of cGAS-STING pathway in sepsis patients and CLP-induced sepsis mouse models." (PMID 36068299, 2022). "With regard to self-DNA, sepsis also induces mitochondrial damage, and host cell death enhances free mtDNAs and nDNAs that could be exposed to cytosolic cGAS, thereby facilitating sepsis hyperinflammation in a vicious cycle." (PMID 34768881, 2021). "Additionally, CLP induced leukopenia, neutropenia and lymphopenia in both WT and cGAS-/- mice, but leukopenia was more prominent in WT than cGAS-/- mice, consistent with the more severe sepsis-induced leukopenia in WT mice." (PMID 34768881, 2021). "Anti-inflammatory sepsis treatment by a cGAS inhibitor might be a promising therapeutic strategy and should be investigated further." (PMID 34768881, 2021). "Inhibition of IFN-I signaling pathways such as RIG-I/MAVS/IFN-I and cGAS/STING/IFN-I may become new effective therapeutic targets for sepsis." (PMID 31205588, 2019). "Likewise, targeting cGAS-STING protects against sepsis-induced multiorgan dysfunction." (PMID 40102400, 2025). "Hence, the lower severity of sepsis in cGAS−/− mice than in WT might be due to the less prominent immune responses against the infection, especially the responses by macrophages, which are one of the major immune cells responsible for sepsis severity." (PMID 40507879, 2025). "In conclusion, cGAS activation by cfDNA from hosts (especially mtDNA) and bacteria was found to induce an additive proinflammatory effect on LPS-activated macrophages which was perhaps responsible for the more pronounced sepsis hyperinflammation observed in WT mice compared with the cGAS-/- group." (PMID 34768881, 2021). "In this study, we demonstrated that fatty acid synthesis induced EC activation via promoting cytosolic mtDNA-related activation of cGAS-STING signaling and pyroptosis, thereby leading to lung injury during sepsis." (PMID 40369168, 2025). "This work is significant as it identifies mtROS/cGAS-STING-IFN-β as a key therapeutic target and repurposes metformin for potential sepsis treatment." (PMID 40905697, 2025). "VDAC1 oligomerization promoted the release of mtDNA to induce EC dysfunction via activating cGAS-STING signaling pathway, thereby leading to lung injury during sepsis." (PMID 40369168, 2025). "At the same time, it also provides a potential therapeutic agent for cGAS-STING pathway-induced related inflammatory diseases, particularly sepsis." (PMID 38904004, 2024). "Studies have indicated that the cGAS-STING pathway is significantly expressed in a variety of inflammatory diseases, such as sepsis, kidney injury and lung injury." (PMID 38904004, 2024). "We found that GUP inhibited the activation of the cGAS-STING pathway by inhibiting the interaction of STING with TBK1 and TBK1 with IRF3, thereby reducing the harm of sepsis." (PMID 38904004, 2024). "Study showed significant activation of cGAS-STING pathway in Cecal Ligation and Puncture (CLP)-induced sepsis." (PMID 38904004, 2024). "This article reports that GUP, the main active constituent of G. uralensis, suppressed the activation of cGAS-STING both in vitro and in vivo, revealing the effect of GUP in regulating cGAS-STING-mediated sepsis." (PMID 38904004, 2024). "Recently, the cGAS-STING pathway has also been found to be involved in response to bacterial infections, including bacterial pneumonia, melioidosis, tuberculosis, and sepsis." (PMID 35095914, 2021). "Hence, a cGAS inhibitor might be an interesting candidate for anti-inflammatory sepsis treatment." (PMID 34768881, 2021).